IRX2-DT (IRX2 divergent transcript)
Synonyms: CEI; IRX2NB; formerly C5orf38
Gene: Long non-coding RNA gene on chromosome 5 (2,752,131 to 2,755,397, forward strand). Ensembl gene ENSG00000186493.
Subcellular location: Secreted
Diseases named in the same sentence as IRX2-DT in open-access papers:
IRX2-DT is named in the same sentence as 14 diseases in open-access papers, as found by Europe PMC text mining. Sharing a sentence is not in itself a finding about the gene and the disease.
IRX2-DT shares sentences with these, for which no sentence is quoted: cancer (2 papers); Alzheimer disease (1); amnestic disorder (1); breast carcinoma (1); cardioembolic stroke (1); cognitive disorder (1); coronary atherosclerosis (1); delirium (1); dementia (1); glioma (1); infection (1); lung carcinoma (1); mental disorder (1); tumor (1).